EVA1A (eva-1 homolog A, regulator of programmed cell death)
Description:
Acts as a regulator of programmed cell death, mediating both autophagy and apoptosis.
Synonyms: FAM176A; TMEM166; FLJ13391
Tractability: Antibody: its Gene Ontology location is reachable by antibodies, with high confidence; UniProt predicts a signal peptide or a membrane-spanning region. PROTAC: ubiquitination databases record sites on it.
Gene: Protein-coding gene on chromosome 2 (75,469,302 to 75,571,036, reverse strand). Ensembl gene ENSG00000115363.
Subcellular location: Endoplasmic reticulum membrane; Lysosome membrane
Subcellular location (Human Protein Atlas): Vesicles; Plasma membrane
Pathways (Reactome):
Metabolism of proteins: Post-translational protein phosphorylation; Regulation of Insulin-like Growth Factor (IGF) transport and uptake by Insulin-like Growth Factor Binding Proteins (IGFBPs)
Gene Ontology:
Molecular function: protein binding
Cellular component: endoplasmic reticulum lumen; endoplasmic reticulum membrane; lysosomal membrane
Genetic constraint (gnomAD): Loss-of-function variants: 7 observed, 10.28 expected, observed/expected ratio (o/e) 0.68, 90% interval 0.39 to 1.28. The upper end of that interval is the gene's LOEUF score, 1.28, which puts it in group 5 of 6, group 1 being the genes least tolerant of losing a copy. Missense variants: 206 observed, 214.6 expected, observed/expected ratio (o/e) 0.96, 90% interval 0.86 to 1.08. Synonymous variants: 90 observed, 91.23 expected, observed/expected ratio (o/e) 0.99, 90% interval 0.83 to 1.18.
Homologues: Orthologues: chimpanzee EVA1A (100% identical), macaque EVA1A (98% identical), pig EVA1A (90% identical), mouse Eva1a (87% identical), rat Eva1a (86% identical), dog EVA1A (84% identical), guinea pig EVA1A (83% identical), rabbit EVA1A (82% identical), tropical clawed frog eva1a (73% identical), zebrafish eva1a (68% identical), zebrafish EVA1A (64% identical). Paralogues in human: EVA1B (47% identical).
Diseases named in the same sentence as EVA1A in open-access papers:
EVA1A is named in the same sentence as 52 diseases in open-access papers, as found by Europe PMC text mining. Sharing a sentence is not in itself a finding about the gene and the disease. The quoted sentences say what the papers report.
hepatocellular carcinoma (10 papers, 2018 to 2025). A malignant tumor that arises from hepatocytes. "In this study, we examine the function of EVA1A, a known hepatocellular carcinoma tumor suppressor, in hepatic lipid metabolism." (PMID 41306774, 2025). "Additionally, hepatocellular carcinoma patients’ resistance to oxaliplatin treatment was linked to the downregulation of miR-125b, which was mediated via its target, EVA1A, thus illustrating how miR-125b regulates its target, EVA1A, to contribute to the possible mechanism of oxaliplatin resistance." (PMID 40136426, 2025). "Other studies have shown that EVA1A can participate in the promotion of CCAAT/enhancer binding proteins alpha (C/EBPα)-mediated autophagy in hepatocellular carcinoma." (PMID 35743108, 2022). "In several cancers, such as hepatocellular carcinoma and non‐small cell lung cancer, the expression of EVA1A is low in carcinoma tissues, and EVA1A can inhibit tumour cell growth through autophagy and apoptosis." (PMID 32969138, 2020). "In the present study, we identified EVA1A as a target of microRNA-125b (miR-125b), a member of a highly conserved family of miRNAs that has been proposed as a biomarker for hepatocellular carcinoma (HCC)." (PMID 29749374, 2018). "When exposed to OA to mimic high lipid loading, primary rat hepatocytes and 2 hepatoma cell lines, HepG2 and Huh7, showed a marked increase in fatty acid uptake and lipid accumulation following EVA1A deletion, along with a notable decrease in fatty acid β-oxidation and ATP generation." (PMID 41306774, 2025). "In contrast to its expression in hepatocellular carcinoma and non‐small cell lung cancer, the EVA1A expression in thyroid cancer tissues is significantly higher than that in the normal thyroid tissue according to The Cancer Genome Atlas (TCGA) database (P < .0001)." (PMID 32969138, 2020). "Previous studies have revealed that, compared to normal tissues, EVA1A is down-regulated in various human tumors, such as pituitary adenoma, myeloma, adrenocortical, pancreatic and hepatocellular carcinomas, as well as gastric, esophageal and lung cancers 39-45." (PMID 32724459, 2020).
non-small cell lung carcinoma (7 papers, 2017 to 2025). A group of at least three distinct histological types of lung cancer, including non-small cell squamous cell carcinoma, adenocarcinoma, and large cell carcinoma. "Overexpression of EVA1A can inhibit tumor cell proliferation by inducing apoptosis in cervical cancer HeLa cells, non-small cell lung cancer H1299 cells, and glioblastoma SHG44, U87, and U251 cell lines." (PMID 36273122, 2022). "Hong Xie and colleagues found that EVA1A protein expression was notably upregulated in a dose-dependent manner in H1299 cells (human non-small cell lung cancer cells)." (PMID 35743108, 2022).
glioblastoma (5 papers, 2019 to 2025). The most malignant astrocytic tumor (WHO grade IV). "EVA1A inhibits glioblastoma cells proliferation by upregulating autophagy via suppressing the mTOR/RPS6KB1 pathway." (PMID 35743108, 2022). "Xue Shen and colleagues transfected the recombinant adenovirus 5-EVA1A vector (ad5-EVA1A) into glioblastoma (GBM) cells to overexpress EVA1A in order to analyse its antitumor activity in vitro." (PMID 35743108, 2022).
liver cancer (5 papers, 2022 to 2025). An epithelial or non-epithelial malignant neoplasm that arises from the liver. "Previous research has shown that EVA1A can enhance resistance to the drug oxaliplatin in liver cancer by inducing autophagy." (PMID 38529374, 2024). "It has been found that EVA1A is significantly downregulated in human tumor tissues such as liver cancer, esophageal squamous cell carcinoma, gastric adenocarcinoma and pancreatic tumors, indicating that it may be involved in the occurrence or development of these tumors." (PMID 36273122, 2022). "Therefore, whether EVA1A can regulate autophagy/NLRP3 to improve liver cancer is a topic worthy of study in the future." (PMID 35743108, 2022).
papillary thyroid cancer (4 papers, 2020 to 2024). "EVA1A promotes papillary thyroid carcinoma progression through activating the Hippo pathway." (PMID 35743108, 2022). "Furthermore, a body of research suggests that EVA1A could potentially stimulate the proliferation and metastasis of papillary thyroid cancer (PTC) by impeding apoptosis, bolstering the Hippo signaling pathway, and instigating Epithelial-mesenchymal transition (EMT)." (PMID 38529374, 2024).
breast carcinoma (3 papers, 2022 to 2023). "However, the detailed underlying mechanisms of EVA1A remain unclear and need further investigation in breast cancer treatment with flubendazole." (PMID 35440104, 2022). "Together, these findings shed a novel mechanism of flubendazole against breast cancer, focusing on the mitochondrial dysfunction and DRP1-mediated mitophagy in breast cancer via targeting EVA1A." (PMID 35440104, 2022). "Collectively, flubendazole suppressed breast cancer by inducing mitochondrial dysfunction through promoting DRP1-mediated mitophagy via upregulating EVA1A, which provides a new mechanism for targeting EVA1A in the treatment of breast cancer." (PMID 35743108, 2022). "Together, flubendazole induces mitochondrial dysfunction and DRP1-mediated mitophagy in breast cancer via targeting EVA1A." (PMID 35440104, 2022). "Similar results were obtained concerning the immunofluorescence analysis of Parkin and TOM20, which indicate that flubendazole induces DRP1-mediated mitophagy via targeting EVA1A in breast cancer." (PMID 35440104, 2022). "In this regard, our results presented herein demonstrate for the first time that EVA1A overexpression induced mitophagy in breast cancer." (PMID 35440104, 2022). "Likewise, flubendazole induces mitochondrial dysfunction and DRP1-mediated mitophagy in breast cancer via targeting EVA1A." (PMID 35440104, 2022). "Interestingly, we demonstrated that excessive DRP1-mediated mitophagy is characterized as a critical event in response to the anti-tumor effects of EVA1A in breast cancer." (PMID 35440104, 2022). "The mechanism of EVA1A regulating autophagy in breast cancer needs to be clarified." (PMID 35743108, 2022). "Moreover, we demonstrated that excessive DRP1-mediated mitophagy played a critical role in response to the anti-tumor effects of EVA1A in breast cancer." (PMID 35440104, 2022). "It has been reported that EVA1A-modulated autophagy can improve breast cancer." (PMID 35743108, 2022). "It has been reported that the mitochondria is involved in cell proliferation and death, suggesting that the mitochondria may be involved in the protective role of EVA1A against breast cancer." (PMID 35743108, 2022). "In summary, our results suggest that DRP1-mediated mitophagy induced by EVA1A overexpression may be the primary contributing factor for mitochondrial damage and dysfunction in breast cancer cells in response to flubendazole treatment, resulting in inhibition of cell proliferation and migration." (PMID 35440104, 2022). "Collectively, EVA1A overexpression triggers excessive DRP1-mediated mitophagy and exerts anti-cancer effects in breast cancer." (PMID 35440104, 2022). "Interestingly, our results support that DRP1-mediated mitophagy is involved in the anti-cancer effects of EVA1A, as evidenced by silencing DRP1 blocks the anti-proliferative and anti-migration effects of EVA1A overexpression in breast cancer." (PMID 35440104, 2022). "EVA1A overexpression promoted DRP1-mediated mitophagy and inhibited breast cancer." (PMID 35743108, 2022).
heart failure (3 papers, 2017 to 2025). Inability of the heart to pump blood at an adequate rate to meet tissue metabolic requirements. "Future studies should be conducted to explore the potential for Eva1a as a therapeutic target in heart failure." (PMID 28151473, 2017). "In summary, the present study demonstrates that Eva1a protects against cardiac remodelling and heart failure." (PMID 28151473, 2017).
lymph node metastasis (3 papers, 2020 to 2024). "Results showed that a high EVA1A expression was related to histological type (P < .001), age (P = .025), tumour size (P = .06) and lymph node metastasis (LNM; P < .001)." (PMID 32969138, 2020). "Finally, we performed a LASSO logistic regression analysis of the gene expression matrix of seven of the THCA cohort from the TCGA database by the presence or absence of lymph node metastasis to finalize the risk scores constructed for the five most relevant genes (EVA1A, SERPINA1, FN1, TNC, MXRA8)." (PMID 35141140, 2021). "Moreover, a significant correlation was observed between EVA1A and the prognosis of PTC with lymph node metastasis (P=0.038< 0.05), establishing it as an independent prognostic factor." (PMID 38529374, 2024).
acute liver failure (2 papers, 2021 to 2022). Rapid deterioration of liver function causing encephalopathy and coagulopathy. "EVA1A regulates embryonic neurogenesis, cardiac remodeling, islet alpha-cell functions, acute liver failure, and hepatitis B virus replication." (PMID 34201121, 2021).
esophageal squamous cell carcinoma (2 papers, 2022 to 2024). Esophageal squamous cell carcinoma (ESCC) is a type of esophageal carcinoma (EC) that can affect any part of the esophagus, but is usually located in the upper or middle third. "Contemporary research has unveiled that the prevalence of EVA1A protein expression in T3/T4 stage esophageal squamous cell carcinoma stands at a substantial 77.8% (21/27), markedly surpassing that in the T1/T2 stage (41.7%, 5/12)." (PMID 38529374, 2024).
multiple myeloma (2 papers, 2020 to 2024). "Previous research by several scholars has analyzed 16 survival-associated autophagy genes (ARGs), including EVA1A, FOXO1, and HIF1, to assess the risk and adverse prognosis of multiple myeloma (MM)." (PMID 38529374, 2024).
Myocardial fibrosis (2 papers, 2017 to 2021). "It has been reported that myocardial fibrosis is related to oxidative stress, so whether EVA1A can protect myocardium through antioxidant stress remains to be studied." (PMID 34201121, 2021). "In our study, none of the mice exhibited myocardial fibrosis on the third day (data not shown); however, partial Eva1a-deficient mice exhibited obvious cardiac fibrosis at 2 weeks." (PMID 28151473, 2017).
myocardial hypertrophy (2 papers, 2017 to 2021). "This is the first study to discover that Eva1a deficiency can cause myocardial hypertrophy, indicating the important role that Eva1a had in maintaining cardiac homeostasis." (PMID 28151473, 2017). "Data from experiments showed that loss of Eva1a in the adult heart increased cardiac fibrosis, promoted cardiac hypertrophy, and led to cardiomyopathy and death." (PMID 28151473, 2017). "In conclusion, the results suggested that EVA1A ameliorated cardiac remodeling through inhibiting cardiac hypertrophy and fibrosis by promoting autophagy via inhibiting mTOR pathway." (PMID 34201121, 2021). "Collectively, these data demonstrated that Eva1a improves cardiac function and inhibits cardiac hypertrophy and fibrosis by increasing autophagy." (PMID 28151473, 2017). "Taken together, these results indicated that Eva1a may exert a beneficial effect on cardiac hypertrophy." (PMID 28151473, 2017). "We carried out pathological analysis to investigate the role of Eva1a in cardiac hypertrophy." (PMID 28151473, 2017).
triple-negative breast carcinoma (2 papers, 2021 to 2022). An invasive breast carcinoma which is negative for expression of estrogen receptor (ER), progesterone receptor (PR), and human epidermal growth factor receptor 2 (HER2). "We previously reported that the anthelmintic drug flubendazole induced autophagy and apoptosis via upregulation of eva-1 homolog A (EVA1A) in triple-negative breast cancer (TNBC) and was repurposed as a novel anti-tumor agent." (PMID 35440104, 2022). "Moreover, flubendazole exhibits anticarcinoma effects in triple-negative breast carcinoma by targeting EVA1A-modulated autophagy and apoptosis." (PMID 34513827, 2021).
atherosclerosis (1 paper, 2023). A disease characterized by the build-up of fatty material and calcium deposition in the arterial wall resulting in partial or complete occlusion of the arterial lumen. "TWIST1 is a basic helix-loop-helix transcription factor that is activated by DF and promotes endothelial dysfunction and atherosclerosis, making it an attractive candidate for the DF-sensitive regulation of EVA1A." (PMID 36794585, 2023).
colorectal cancer (1 paper, 2024). A primary or metastatic malignant neoplasm that affects the colon or rectum. "The purpose of this study was to investigate the potential of EVA1A as a prognostic biomarker for Colorectal cancer (CRC)." (PMID 38529374, 2024). "In addition, in TCGA database, a significant correlation was found between high EVA1A expression and reduced overall survival in 597 CRC patients (P=0.0041< 0.05) (Expression of EVA1A in colorectal cancer - The Human Protein Atlas)." (PMID 38529374, 2024).
endothelial dysfunction (1 paper, 2023). In vascular diseases, endothelial dysfunction is a systemic pathological state of the endothelium (the inner lining of blood vessels) and can be broadly defined as an imbalance between vasodilating and vasoconstricting substances produced by (or acting on) the endothelium. "Here, we sought to investigate the role of EVA1A in WSS-regulated endothelial dysfunction and regulation of autophagy in ECs exposed to flow." (PMID 36794585, 2023).
fibrosis (1 paper, 2017). the formation of excess fibrous connective tissue in an organ or tissue in a reparative or reactive process. "On day 3 after tamoxifen induction, cardiac fibrosis in Eva1a-deficient mice may be too acute for compensatory mechanisms to be effective." (PMID 28151473, 2017).
glioma (1 paper, 2023). A benign or malignant brain and spinal cord tumor that arises from glial cells (astrocytes, oligodendrocytes, ependymal cells). "For the sake of clarifying the expression of BMGs in glioma, this study screened 9 BMGs that were upregulated in glioma (FBN2, FREM3, Lamb4, MEP1A, MMP1, MMP7, OPTC, EVA1A, and ADAMTS20) from TCGA -GTEX expression matrix." (PMID 37335645, 2023).
Hepatic steatosis (1 paper, 2025). Steatosis is a term used to denote lipid accumulation within hepatocytes. "Liver histology and Oil Red O (ORO) staining demonstrated that Eva1a−/− mice developed significant hepatic steatosis." (PMID 41306774, 2025). "To further validate the protective function of EVA1A against MASLD in vivo, we employed adeno-associated virus-mediated Eva1a overexpression in ob/ob mice, a well-established model of obesity and fatty liver." (PMID 41306774, 2025). "Liver-specific Eva1a knockout in healthy mice directly induced hepatic steatosis; however, hepatic Eva1a overexpression in ob/ob mice largely alleviated the hepatic steatosis, demonstrating EVA1A’s protective role in liver lipid metabolism." (PMID 41306774, 2025). "Pathology data indicated that HCC patients with down-regulated EVA1A were mostly accompanied by hepatic steatosis." (PMID 41306774, 2025). "Collectively, these findings demonstrate that targeted deletion of Eva1a in the liver leads to the development of hepatic steatosis in mice." (PMID 41306774, 2025). "Based on the observations that Eva1a knockout triggered hepatic steatosis in mice, we postulated that EVA1A plays a protective role against MASLD." (PMID 41306774, 2025). "This enabled the identification of EVA1A as a pivotal regulator of overall hepatic lipid homeostasis and a critical target for treating fatty liver disease." (PMID 41306774, 2025). "We constructed liver-specific Eva1a knockout mice and the mice develop hepatic steatosis." (PMID 41306774, 2025).
Hyperglycemia (1 paper, 2025). An increased concentration of glucose in the blood. "In contrast, high glucose stimulation does not alter EVA1A RNA levels, suggesting that EVA1A expression specifically responds to circulating lipids rather than common sugars, despite the potential development of hyperglycemia and insulin resistance in advanced MASLD stages." (PMID 41306774, 2025).
Lymphatic Metastasis (1 paper, 2021). Transfer of a neoplasm from its primary site to lymph nodes or to distant parts of the body by way of the lymphatic system. "Subsequent prognostic analysis showed that only EVA1A had prognostic significance in THCA with or without lymphatic metastasis." (PMID 35141140, 2021).
pancreatic cancer (1 paper, 2022). "The role and mechanism of EVA1A in pancreatic cancer needs further study." (PMID 35743108, 2022). "The ectopic expression of EVA1A in pancreatic tumors might promote the occurrence and development of tumors, which needed further research." (PMID 35743108, 2022). "EVA1A may become a potential target for the diagnosis and treatment of pancreatic cancer." (PMID 35743108, 2022).
steatosis (1 paper, 2025). Increased lipid within the cytoplasm of cells. "Contrary to the phenotype observed in Eva1a-LKO mice, Eva1a overexpression suppressed both transcription and expression of CD36, while enhancing those of CPT1A, thereby mitigating steatosis in the livers of ob/ob mice." (PMID 41306774, 2025).